MAOB (monoamine oxidase B)
Description:
Catalyzes the oxidative deamination of primary and some secondary amines such as neurotransmitters, and exogenous amines including the tertiary amine, neurotoxin 1-methyl-4-phenyl-1,2,3,6-tetrahydropyridine (MPTP), with concomitant reduction of oxygen to hydrogen peroxide and participates in the metabolism of neuroactive and vasoactive amines in the central nervous system and peripheral tissues. Preferentially degrades benzylamine and phenylethylamine.
Tractability: Small molecule: an approved drug acts on it; a structure with a bound ligand is known; a high-quality ligand is known; it has a high-quality binding pocket; it belongs to a druggable protein family. Antibody: UniProt predicts a signal peptide or a membrane-spanning region. PROTAC: ubiquitination databases record sites on it; its protein half-life has been measured; a small molecule that binds it is known.
Target class: Enzyme; Oxidoreductase
Chemical probes: CHEMBL3360732, CHEMBL470226, PD082508, PD083926, PD134437, PD134438, PD134439
Safety:
Unwanted effects reported when the protein is acted on. In parentheses: how it was acted on, where the effect was seen, and who reports it.
diarrhoea (inhibition; gastrointestinal; source: Brennan et al. (2024))
dizziness (inhibition; central nervous system; source: Brennan et al. (2024))
dyskinesia (inhibition; central nervous system; source: Brennan et al. (2024))
hallucinations (inhibition; central nervous system; source: Brennan et al. (2024))
Hypertension (inhibition; cardiovascular; source: Brennan et al. (2024))
Gene: Protein-coding gene on chromosome X (43,766,400 to 43,882,559, reverse strand). Ensembl gene ENSG00000069535.
Subcellular location: Mitochondrion outer membrane
Pathways (Reactome):
Metabolism: Biogenic amines are oxidatively deaminated to aldehydes by MAOA and MAOB
Gene Ontology:
Molecular function: monoamine oxidase activity; primary methylamine oxidase activity; protein binding; electron transfer activity; oxidoreductase activity
Biological process: substantia nigra development; dopamine catabolic process; hydrogen peroxide biosynthetic process; phenylethylamine catabolic process; serotonin metabolic process
Cellular component: mitochondrion; mitochondrial envelope; mitochondrial outer membrane
Homologues: Orthologues: chimpanzee MAOB (99% identical), macaque MAOB (98% identical), dog MAOB (95% identical), rabbit MAOB (93% identical), pig MAOB (89% identical), guinea pig MAOB (89% identical), mouse Maob (89% identical), rat Maob (89% identical), tropical clawed frog maob (73% identical), zebrafish mao (70% identical), zebrafish si:ch211-127i16.2 (22% identical), Caenorhabditis elegans spr-5 (20% identical), and 11 more. Paralogues in human: MAOA (72% identical), KDM1A (22% identical), KDM1B (20% identical), IL4I1 (20% identical), PAOX (19% identical), SMOX (18% identical), PPOX (15% identical).
Diseases named in the same sentence as MAOB in open-access papers:
MAOB is named in the same sentence as 211 diseases in open-access papers, as found by Europe PMC text mining. Sharing a sentence is not in itself a finding about the gene and the disease. The quoted sentences say what the papers report.
Parkinson disease (285 papers, 2008 to 2026). A progressive degenerative disorder of the central nervous system characterized by loss of dopamine producing neurons in the substantia nigra and the presence of Lewy bodies in the substantia nigra and locus coeruleus. "MAOB, for example, encodes an enzyme that helps break down neurotransmitters (often in the brain) and is a target for treating Parkinson’s disease symptoms." (PMID 41345545, 2025). "The MAOB gene encodes monoamine oxidase B, an enzyme responsible for the degradation of dopamine and associated with neurodegenerative diseases such as Alzheimer’s and Parkinson’s disease." (PMID 39595853, 2024). "For instance, the MAOB rs1799836 A‐allele is thought to enhance the removal of MAOB intron 13 in Parkinson's disease patients." (PMID 38520217, 2024). "For instance, individuals with the MAOB rs1799836 G‐allele in Parkinson's disease have a higher likelihood of developing dyskinesia compared to those with the A‐allele, potentially due to the G‐allele's association with reduced MAOB activity in the brain." (PMID 38520217, 2024). "Monoamine oxidase-B (MAO-B) is an enzyme associated with Parkinson’s and has been classed as a pharmacological target for its treatment, as its inhibition increases dopamine levels." (PMID 38698940, 2024). "The brain protein IREB2 is associated with Alzheimer’s disease, whereas the brain protein MAOB is associated with both Alzheimer’s and Parkinson’s diseases." (PMID 35259090, 2022). "The genetic variability of the monoamine oxidase B gene (MAOB) has also been suggested as a risk factor for Parkinson's disease." (PMID 23754977, 2013). "Moreover, silymarin’s ability to hamper monoamine oxidase-B (MAO-B) enzymatic activity adds to the neuroprotective mechanisms of silymarin which counteract the loss of dopamine in parkinsonism." (PMID 36014565, 2022). "The monoamine oxidase B (MAO-B) enzyme is linked with Parkinson's disease." (PMID 36518132, 2022). "The examination of iPSC‐derived DA neurons from a pair of monozygotic twins discordant for Parkinson's disease, while carrying a distinct predisposing mutation, yielded significantly different findings in monoamine oxidase B (MAO‐B) activity and DA availability." (PMID 27690184, 2017). "SNP variants in FGF20 and MAOB show evidence of statistical interactions, which emphasizes the importance of considering them jointly in the genetic analysis of Parkinson's disease, and illustrates the potential patterns of biological interactions contributing to the risk of Parkinson's disease." (PMID 23754977, 2013). "Monoamine oxidase-B (MAO-B) is an enzyme found in astrocytes and has been implicated in the neurodegenerative process associated with aging and in neurodegenerative diseases including Parkinson’s and Alzheimer’s disease." (PMID 23326597, 2013). "This MAOB SNP was found to be associated with emotional regulation and Parkinson's disease." (PMID 24453887, 2013). "The patient was initially diagnosed with Parkinson’s disease (PD) and treated with selegiline, a monoamine oxidase B (MAO-B) inhibitor." (PMID 40162155, 2025). "Parkinson’s disease (PD) symptoms are frequently treated with monoamine oxidase-B (MAO-B) inhibitors." (PMID 40429850, 2025). "Regarding WM prescription of patients with PD, the frequently prescribed anti-Parkinson drugs were dopa and dopa derivatives, followed by dopamine agonists, amantadine derivatives, monoamine oxidase B inhibitors, and COMT inhibitors." (PMID 40428042, 2025). "DA agonists such as pramipexole and the selective monoamine oxidase B inhibitor selegiline, commonly used to treat Parkinson’s disease, have also been found to be effective for ADHD by enhancing DA neurotransmission at the synapse." (PMID 40078279, 2025). "There are many therapeutic options for treating Parkinson’s disease, including therapy with carbidopa-levodopa, monoamine oxidase-B inhibitors, and dopamine agonists." (PMID 40807329, 2025).
Parkinson disease (continued). "Vitexin also inhibits the monoamine oxidase B (MAO-B) enzyme, increasing striatal dopamine levels and improving behavioral deficits in experimental Parkinson’s disease models." (PMID 40569946, 2025). "MAO-B inhibitors are used to decrease MAOB activity and increase dopamine levels, therefore mitigating symptoms in Parkinson’s disease patients." (PMID 41345545, 2025). "Monoamine oxidase-B (MAO-B) inhibitors play a significant role in the management of Parkinson’s disease (PD), providing moderate symptomatic relief by increasing dopamine availability in the brain." (PMID 41304922, 2025). "The treatment of Parkinson’s disease targets α-synuclein to reduce aggregation and dopamine degradation by utilizing monoamine oxidase B inhibitors (MAO-B), neuroinflammation, and iron accumulation to decrease oxidative stress and neuronal cell death." (PMID 39199163, 2024). "Monoamine oxidase B (MAO-B) inhibitors are widely used as part of combination drug therapy for Parkinson’s disease." (PMID 39795958, 2024). "Monoamine oxidase B (MAO-B) has been recognized as a target for developing anti-Parkinson’s disease drugs." (PMID 36840231, 2023). "In rat’s brain tissues, a small dose of reserpine initiates symptoms of Parkinson’s disease by increasing monoamine oxidase B (MAO-B) level, and decreasing dopamine." (PMID 37189742, 2023). "Unsaturated ketone derivatives are known as monoamine oxidase B (MAO-B) inhibitors, a potential drug target for Parkinson’s disease." (PMID 37720619, 2023). "Selegiline and rasagiline are two selective monoamine oxidase B (MAO-B) inhibitors used in the treatment of Parkinson’s disease." (PMID 37686140, 2023). "Selegiline (previously called L-deprenyl) is a clinically widely used, irreversible and selective inhibitor of MAOB, which is primarily used to treat Parkinson’s disease and depression." (PMID 37299505, 2023). "Monoamine oxidase B inhibitors represent an important treatment option in the management of Parkinson’s disease (PD), both in the early and in the advanced stages of motor complications." (PMID 35190544, 2022). "Three monoamine oxidase B inhibitors (MAO-BIs) are now commercially available in many countries for the management of motor symptoms in patients with Parkinson’s disease (PD)." (PMID 35697709, 2022). "Selegiline, a monoamine oxidase B (MAO-B) inhibitor used in the treatment of early-stage Parkinson’s disease, is proposed to act as a neuroprotectant by reducing the antioxidant burden of the cell." (PMID 35867211, 2022). "Methylphenidate (a dopamine transporter blocker) and rosagiline (a monoamine oxidase-B inhibitor) treatments also improved fatigue scores in Parkinson’s disease patients by enhancing the dopaminergic signalling in the striatum." (PMID 34423297, 2021). "Monoamine oxidase-B (MAO-B) is a well-established therapeutic target for Parkinson’s disease (PD); however, previous clinical studies on currently available irreversible MAO-B inhibitors have yielded disappointing neuroprotective effects." (PMID 34611843, 2021). "The evaluation of monoamine oxidase B (MAO-B) inhibitors has aroused considerable interest as therapeutic agents for neurodegenerative diseases such as Parkinson’s." (PMID 33921982, 2021). "As reported, Maackiain can dampen human monoamine oxidase B (MAO‐B) enzyme for the treatment of disorders like Alzheimer disease, Parkinson's disease and depression." (PMID 32939977, 2020). "In fact, the expression of MAOB is increased in Alzheimer’s disease and Parkinson’s disease, and MAOB inhibitors have been investigated as treatments for these diseases." (PMID 32094232, 2020). "Monoamine oxidase B (MAO-B) inhibitors have an established role in the treatment of Parkinson’s disease as monotherapy or adjuvant to levodopa." (PMID 31562557, 2020). "In the brain of primates, MPTP is converted into MPP+ (1-methyl-4-phenylpyridinium) by monoamine oxidase B (MAO-B), causing parkinsonism by killing DA neurons in substantia nigra." (PMID 33414358, 2020).
Parkinson disease (continued). "The current pharmacological treatments for Parkinson’s disease only offer symptomatic relief to the patients and are based on the administration of levodopa and catechol-O-methyltransferase or monoamine oxidase-B inhibitors (IMAO-B)." (PMID 31336891, 2019). "One of the first reports of polyphenol-drug synergy in rodents showed EGCG favorably interacting with rasagiline, an irreversible inhibitor of dopamine-metabolizing monoamine oxidase B (MAO-B) for the treatment of Parkinson’s disease." (PMID 30995776, 2019). "Rasagiline is a monoamine oxidase B inhibitor with demonstrated efficacy and safety in patients with Parkinson’s disease (PD)." (PMID 30689042, 2019). "MAOB, an activity of which in mitochondrial function is thought to be related to Parkinson’s disease, binds to the outer membranes of mitochondria and is widely distributed among tissue types." (PMID 29158336, 2018). "The enzyme monoamine oxidase B (MAO-B) has been reported as a therapeutic target for the treatment of Parkinson's disease and is also a brain glial biomarker." (PMID 30693065, 2018). "Selegilin (SEL), an irreversible monoamine oxidase-B (MAO-B) inhibitor used to help control the symptoms of Parkinson's disease, served as a positive control reagent at an effective concentration of 10 μM." (PMID 30700973, 2018). "In both Alzheimer’s and Parkinson’s patients, monoamine oxidase B (MAO-B) activity is elevated and MAO-B-mediated dopamine metabolism pathway leading to H2O2 generation would cause oxidative stress and reactive oxygen species (ROS)-mediated damage." (PMID 27769241, 2016). "Although it is not a confirmed susceptibility gene, increased levels of monoamine oxidase B (MAO) mRNA and enzymatic activity have been reported in platelets from patients with both Parkinson’s and Alzheimer’s diseases." (PMID 25980689, 2015). "Monoamine oxidase B inhibitors (MAO-BIs) are used in the early management of Parkinson's disease (PD)." (PMID 26557867, 2015). "Selegiline (SEL, L-deprenyl), a monoamine oxidase-B (MAO-B) inhibitor, is a useful anti-Parkinson drug both in monotherapy and as an adjunct to levodopa therapy." (PMID 25268350, 2014). "Preliminary clinical observations suggest that rasagiline, a monoamine oxidase-B inhibitor, improves olfaction in Parkinson's disease." (PMID 23573275, 2013). "In this study, rasagiline was used as a positive control drug for it is a specific monoamine oxidase B inhibitor and used as a monotherapy in early Parkinson's disease or as an adjunct therapy in more advanced cases." (PMID 24159358, 2013). "These compounds displayed superior inhibition compared to selegiline, suggesting they may offer enhanced efficacy for therapeutic interventions targeting diseases related to excessive monoamine oxidase B activity, such as Parkinson’s disease." (PMID 41516245, 2025). "Antibiotics such as antimycin A, oligomycin, and monoamine oxidase B (MAO-B) inhibitors used in Parkinson’s disease, and reactive oxygen species (ROS) inducers such as menadione have also been investigated for their potential to disrupt mitochondrial metabolism and reduce tumour viability." (PMID 39316249, 2025). "A clearer understanding of MAOB’s role in Parkinson’s may help optimize the use of MAOB inhibitors and support the development of new therapies that more precisely target its activity or expression." (PMID 40807329, 2025). "In relation to the current therapeutic strategies, the targeting of monoamine oxidase B (MAOB) inhibitors may contribute to potentially promising therapeutic solutions for Parkinson’s disease." (PMID 39339333, 2024). "Our previous study showed that ASE extracts could inhibit monoamine oxidase B (MAO-B), making them useful for treating several disorders like Alzheimer’s disease (AD), Parkinson’s disease, stroke, and depression." (PMID 36865944, 2023).
Parkinson disease (continued). "Garcinol was found to be an inhibitor of monoamine oxidase B (MAO-B), and as such, it might be helpful in Parkinson’s disease treatment by retarding dopamine depletion." (PMID 37359709, 2023). "Monoamine oxidase B (MAO-B) inhibitors are used to control Parkinson’s disease (PD)." (PMID 37935702, 2023). "Increased MAOB activity might be involved in pathophysiological processes of certain neurodegenerative diseases such as Alzheimer’s and Parkinson’s diseases." (PMID 36313990, 2022). "Catalyzing dopamine by the enzyme monoamine oxidase-B (MAO-B), which is increased in the brain, is the cause of decreased dopamine levels, hence indicating MAO-B is a good target to maintain dopamine levels in Parkinson's diseases." (PMID 35310033, 2022). "Specifically, MAOB has been proposed as a possible therapeutic target for AD due to its association with aberrant GABA production, but it also has therapeutic relevance for Parkinson’s disease due to its role in dopamine depletion." (PMID 34017039, 2021). "Anti-dementia protective drugs such as the cholinesterase inhibitors tacrine, donezepil, and selegiline, as well as selective monoamine oxidase B inhibitors, are widely used for the treatment of Parkinson’s disease, mainly relying on their ability to interact with the GAPDH apoptotic cascade." (PMID 32331439, 2020). "Moreover, MAOB catalyzes the conversion of MPTP into 1-methyl-4-phenylpyridine (MPP+) which is responsible for parkinsonism in intravenous drug users." (PMID 30214392, 2018). "Monoamine oxidase-B (MAO-B) inhibitors are widely used in the treatment of Parkinson’s disease." (PMID 28069007, 2017). "Monoamine oxidase-B inhibitors (MAO-BIs) are used for the initial therapy of Parkinson’s disease." (PMID 27341283, 2016). "However, GFAP levels have been correlated with levels of monoamine oxidase B (MAO-B) in post-mortem Parkinson’s brains, suggesting that MAO-B could be used as a potential marker of astrocytic reactivity." (PMID 39404391, 2024). "Monoamine oxidase B (MAO-B) serves as a critical target in the management of neurodegenerative diseases (NDDs) such as Alzheimer’s and Parkinson’s due to its role in regulating oxidative stress and dopamine metabolism." (PMID 40737296, 2025). "This prodrug has been shown to inhibit both AChE and BuChE, which, by decarbamylating this molecule, releases a phenol derivative of rasagiline, a monoamine oxidase B inhibitor (MAO-B), which is also used in Parkinson’s disease for its neuroprotective effect." (PMID 37896142, 2023). "Instead, MAOB mediates the aberrant synthesis of GABA and hydrogen peroxide (H2O2) in reactive astrocytes of Parkinson’s disease (PD)." (PMID 35457272, 2022). "Walnut is thought to have neuroprotective effects because it can block the monoamine oxidase B (MAO-B) enzyme, which increases oxidative stress in people with Parkinson’s disease." (PMID 36299886, 2022). "An alternative neuroinflammation readout is provided by PET tracers binding to monoamine oxidase B (MAO-B) in astrocytes, which has indicated increased astrocytosis in early stages of Alzheimer’s disease and Parkinson’s disease." (PMID 33846962, 2021). "Selegiline [(−)deprenyl], a selective and irreversible inhibitor of monoamine oxidase B (MAO-B), was approved for the treatment of Parkinson disease and major depressive disorder by the Food and Drug Administration (FDA) decades ago." (PMID 33799684, 2021). "It has been documented that F. assa-foetida resin can potentially inhibit monoamine oxidase B (MAO-B), and it can be used in the therapy of neurodegenerative diseases such as Parkinson's and Alzheimer's diseases." (PMID 33062002, 2020). "In Parkinsonism induced by administration of MPTP, 1-methyl-4-phenyl-1,2,3,6-tetrahydropyridine (a protoxin) undergoes catalytic conversion by monoamine oxidase B (MAO B), which is self-inactivated during this process." (PMID 33321831, 2020).